IGFBP2 (insulin like growth factor binding protein 2)
Diseases named in the same sentence as IGFBP2 in open-access papers (continued):
Sharing a sentence is not in itself a finding about the gene and the disease.
ovarian carcinoma (38 papers, 2005 to 2025). A malignant neoplasm originating from the surface ovarian epithelium. "Although there is no experimental evidence for the positive association between insulin and ovarian cancer, some studies have shown that the increased serum levels of IGF-1, IGF-1R, and IGFBP-2 were associated positively in patients with ovarian cancer." (PMID 25866823, 2015). "Previous studies had shown that IGFBP2 was associated with ovarian cancer and overexpressed in malignant ovarian tissue as well as in the serum and cystic fluid of ovarian cancer patients, suggesting that IGFBP2 plays an important role in ovarian cancer biology." (PMID 40075946, 2025). "Currently, a NCI-sponsored Phase I clinical trial is in progress to test the safety and immunogenicity of an IGFBP2-encoding DNA plasmid-based vaccine in patients with advanced stage or recurrent ovarian cancer, with the hopes of generating an IGFBP2-specific Th1 immune response (NCT01322802)." (PMID 26317790, 2015). "In ovarian cancer cells, COL11A1 had been shown to regulate the TGF-β3 activation of cancer-associated fibroblasts through the NF-κB/IGFBP2 axis." (PMID 40075946, 2025). "In ovarian cancer cells, COL11A1 modulates TGF-β3 via the NF-κB/IGFBP2 axis, thereby activating cancer-associated fibroblasts and influencing tumor development and migration." (PMID 36843929, 2023). "In preclinical studies, when IGFBP-2 was added to ovarian cancer cells, increased cell proliferation was noted and multiple MAP kinase signaling pathways were activated including Raf, MEK, ERK1/2, and Elk-1." (PMID 36230617, 2022). "In ovarian cancer, it activates cancer-associated fibroblasts via the TGF-β3-mediated NF-κB/IGFBP2 pathway." (PMID 36266702, 2022). "Since IGFBP2 is a secretory protein, it has been also observed that serum IGFBP2 was elevated in cancer patients compared to healthy individuals for ovarian cancer, colorectal cancer, and lung cancer." (PMID 28036255, 2017). "Other studies have also shown that IGF-1 and IGFBP-2 in human ovarian cancer cell lines resulted in the induction of proliferation and invasion through phosphorylation of AKT and ERK1/2." (PMID 25866823, 2015). "Clinically, an elevated serum level of IGFBP-2 was shown to correspond with poorer prognosis, suggesting prognostic value of IGFBP-2 in ovarian cancer." (PMID 26217584, 2015). "Serum IGFBP-2 can be used for prediction of chemotherapy response and prognosis in ovarian cancer and acute lymphoblastic leukemia." (PMID 23165420, 2013). "IGFBP-2 is dramatically increased in the serum and ovarian cyst fluid of women with epithelial ovarian cancer and is involved in stimulation of cell growth." (PMID 22927847, 2012). "Other studies have shown that IGFBP-2 expression level in epithelial ovarian cancers is up to 38-fold higher than in normal ovarian epithelium." (PMID 22927847, 2012). "IGFBP-2 is overexpressed in ovarian malignant tissues and in the serum and cystic fluid of ovarian cancer patients, indicating a role in the biology of ovarian cancer." (PMID 20069126, 2010). "Increased protein levels for Timp1, Lcn2, Igfbp2, Pfn1, and Sparc were observed in ovarian tumor tissues isolated from K-ras/Pten and Pten/Apc ovarian cancer mouse models compared to control tissue lysates." (PMID 19936259, 2009). "Although further investigations of molecular mechanisms are required, our findings using siRNA study support IGFBP2 as a novel target for the treatment of ovarian cancer." (PMID 15686601, 2005). "We then designed small interference RNA (siRNA) molecules that attenuated IGFBP2 expression in PA-1 ovarian cancer cells, which have a high level of endogenous IGFBP2." (PMID 15686601, 2005). "In this study, we showed that IGFBP2 was significantly overexpressed in invasive ovarian carcinomas compared with borderline ovarian tumors as well as normal ovarian tissues and that IGFBP2 increases invasion capability of ovarian cancer cells." (PMID 15686601, 2005).
ovarian carcinoma (continued). "Using western blotting and tissue microarray analyses, we showed that IGFBP2 was frequently overexpressed in ovarian carcinomas compared with normal ovarian tissues." (PMID 15686601, 2005). "In this study, we found that overexpression of IGFBP2 enhanced the invasiveness of ovarian cancer cells." (PMID 15686601, 2005). "Further, attenuation of IGFBP2 expression by siRNA reduced the invasiveness of ovarian cancer cells." (PMID 15686601, 2005). "High levels of IGFBP2 were detected in the serum or cystic fluid from patients with ovarian cancer compared with those with benign and borderline tumors." (PMID 15686601, 2005). "High serum levels of IGFBP-2 correlated with higher stage ovarian cancer and poorer prognosis." (PMID 36230617, 2022). "Similarly, augmented IGFBP2 serum levels are correlated with poorer clinicopathological features and worse prognosis in epithelial ovarian cancer." (PMID 33282953, 2020). "Screening of 34 human ovarian cancer cell lines revealed that high expression of Yes, Lyn, Eph2A, caveolin-1 and 2, moesin, annexin-1, and uPA, and low expression of insulin-like growth factor-binding protein 2 (IGFBP2) render the cells sensitive to Dasatinib treatment." (PMID 30791462, 2019). "Previous studies show that circulating IGFBP‐2 levels in women with ovarian cancer correlate with tumour tissue IGFBP‐2 mRNA levels 38, and in patients with colorectal cancer undergoing resection, elevated presurgery concentrations return to normal after resection." (PMID 29722920, 2018). "Furthermore, serum IGFBP-2 levels are characteristically elevated in ovarian cancer patients and correlate with the stage of disease as well as with the prognosis." (PMID 26336825, 2015). "Interestingly, in the same study, the authors demonstrate that the expression of IGFBP2 is related to the type of ovarian cancer, for example, 80% of serous carcinoma had elevated IGFBP2 whereas 80% of clear cell carcinoma had low IGFBP2 levels." (PMID 25774149, 2015). "In combination, these findings suggest that IGFBP-2 is involved in the pathogenesis of ovarian carcinoma and, consequently, it may serve as a circulating biomarker." (PMID 26336825, 2015). "IGFBP2 has also been shown to promote invasion of ovarian cancer cells." (PMID 26097693, 2015). "IGFBP-2 was shown to contribute to ovarian cancer cells invasion in vitro." (PMID 26217584, 2015). "Furthermore, in vitro treatment of ovarian cancer cells with IGFBP-2 was shown to stimulate cell growth and potentiated the activation of multiple signaling pathways involved in cell proliferation." (PMID 26217584, 2015). "Moreover, studies in NIH-OVCAR3 cells have shown that IGF-I and IGFBP-2 promote ovarian cancer cell growth and invasiveness." (PMID 22927847, 2012). "Finally, it was demonstrated that IGFBP-2 relative mRNA expression was 38-fold higher in ovarian cancer than in NOSE." (PMID 20069126, 2010). "CD14, and IGFBP2 have been previously assayed in serum from ovarian cancer patients." (PMID 19936259, 2009). "The purpose of this study was to assess the role of increased IGFBP2 in ovarian cancer cells." (PMID 15686601, 2005). "We therefore showed that IGFBP2 enhances the invasion capacity of ovarian cancer cells." (PMID 15686601, 2005). "Taken together, these data suggest an important role for IGFBP2 in the biology of ovarian cancer." (PMID 15686601, 2005). "To test whether increased IGFBP2 contributes to the highly invasive nature of ovarian cancer cells, we generated IGFBP2-overexpressing cells from an SKOV3 ovarian cancer cell line, which has a very low level of endogenous IGFBP2." (PMID 15686601, 2005). "AuNPs inhibit ovarian carcinoma invasiveness by targeting key oncogenic pathways: impeding MAPK signaling, suppressing EMT-associated proteins, and disrupting the IGFBP2/mTOR/PTEN autoregulatory axis, downregulating IGFBP2, suppressing PI3K/AKT/mTOR activation, and reactivating PTEN." (PMID 41018109, 2025).
ovarian carcinoma (continued). "However, the protein level of IGFBP2 was shown to be upregulated in ovarian cancer." (PMID 37199034, 2023). "Insulin-like growth factor binding proteins (IGFBP) IGFBP-1, IGFBP-2 and IGFBP-3 were increased by leptin treatment in both ovarian cancer cells." (PMID 37155466, 2023). "An increase in IL-3 and IL-10 expressions, insulin-like growth factor binding proteins (IGFBP) IGFBP-1, IGFBP-2 and IGFBP-3 levels were detected in both ovarian cancer cell lines with leptin administration." (PMID 37155466, 2023). "Previous studies reported that COL11A1 modulates the NF-κB/IGFBP2/TGF-β3 cascade to promote EMT and activate the CAFs in ovarian cancer." (PMID 36266702, 2022). "A combined model of insulin-like growth factor-binding protein-2 (IGFBP-2), lecithin cholesterol acyltransferase (LCAT), and CA125 outperformed CA125 detection alone for the earlier detection of ovarian cancer in terms of the sensitivity." (PMID 36233339, 2022). "In four ovarian cancer patients treated with MV-NIS, IFN-γ and IL-4 responses against the tumor antigens FRα and IGF binding protein 2 (IGFBP2) were detected by ELISPOT." (PMID 33535479, 2021). "For example, elevated IGFBP-2 and reduced IGF-1 levels or high levels of an IGFBP-2/IGF-1 ratio were shown to stratify an ovarian cancer patient subgroup with poor prognosis." (PMID 28143425, 2017). "Moreover, serum IGFBP-2 levels are elevated in women with early- and advanced-stage ovarian cancer as compared to controls and to patients with benign gynecological conditions, indicating that IGFBP-2 may be useful as a serum biomarker for detection and monitoring of epithelial ovarian cancer." (PMID 22927847, 2012). "IGFBP-2 and IGFBP-3 are the most common binding proteins involved in ovarian cancer metabolism." (PMID 36230617, 2022). "A detailed examination of ovarian cancers observed that IGFBP2 expression did not correlate with stage of disease, with similar proportions of tumors having low or high expression of IGFBP2 at all stages." (PMID 25774149, 2015). "Though elevated serum levels of IGFBP2 have been demonstrated in a number of cancers, including ovarian, this is the first evidence that IGFBP1 levels increase in serum or plasma of patients with ovarian cancer." (PMID 20559444, 2010). "Thus, IGFBP-2 levels were determined in the serum of EOC patients and found to positively correlate with cancer antigen 125 (CA125), a widely used marker for ovarian cancer follow-up." (PMID 20069126, 2010). "Insulin-like growth factor binding protein 2 (IGFBP2) is overexpressed in ovarian malignant tissues and in the serum and cystic fluid of ovarian cancer patients, suggesting an important role of IGFBP2 in the biology of ovarian cancer." (PMID 15686601, 2005).
lung carcinoma (34 papers, 2012 to 2026). "In lung cancer, high expression of IGFBP2 is associated with poor survival and metastasis of the patients." (PMID 38918360, 2024). "More importantly, IGFBP2 is highly expressed in lung tumors and blood of patients with lung cancer, and the high level of IGFBP2 is associated with unfavorable survival and metastasis of lung cancer patients." (PMID 38918360, 2024). "It has been found to be overexpressed in a broad spectrum of tumors including lung cancer wherein higher plasma levels of IGFBP2 have been positively associated with tumor size, lymph node metastasis, advanced tumor stage, and shorter overall survival." (PMID 37784035, 2023). "IGFBP2 is causally associated with dasatinib resistance and is used as a biomarker for the identification of dasatinib responders among patients with lung cancer." (PMID 28977895, 2017). "Plasma IGFBP2 levels were determined blindly by enzyme-linked immunosorbent assay in 80 lung cancer patients and 80 case-matched healthy controls for comparison." (PMID 24069370, 2013). "The AUC of using IGFBP-2 as diagnostic biomarker for lung cancer was 0.608 (95% CI=0.504–0.712, p=0.047), the sensitivity and specificity were 54.1 and 72.5%, respectively, with the cutoff value of 1,173.033 ng/ml." (PMID 23165420, 2013). "We analyzed blood samples for IGFBP2 levels from an additional 84 patients with lung cancer and then tested for associations between blood IGFBP2 levels and clinical parameters in all 164 lung cancer patients." (PMID 24069370, 2013). "Our results showed that the blood concentration of IGFBP2 was significantly increased in lung cancer patients and that a high IGFBP2 concentration in the patients’ blood was associated with short overall survival." (PMID 24069370, 2013). "Additionally, serum IGFBP2 level is recognized as a diagnostic biomarker of severe malnutrition in patients with advanced lung cancer." (PMID 38918360, 2024). "Additionally, IGFBP-2 has been studied in association with anti-IGFBP-2 autoantibodies in lung cancer." (PMID 35198099, 2022). "Furthermore, IGFBP2 expression was found to be associated with metastasis and poor overall survival in lung cancer." (PMID 29500455, 2018). "This study aims to determine whether IGFBP2 is elevated in blood samples of lung cancer patients and whether its level is associated with clinical outcomes." (PMID 24069370, 2013). "When serum IGFBP-2 and anti-IGFBP-2 antibodies were detected simultaneously, the sensitivity of the assay was raised to 85.7%, and the specificity was 57.5% indicating that use of both serum IGFBP2 and anti-IGFBP-2 antibody can increase the diagnostic efficacy in lung cancer." (PMID 23165420, 2013). "The purpose of this study was to evaluate whether autoantibodies to IGFBP-2 can be used as diagnostic markers in lung cancer." (PMID 23165420, 2013). "A high circulating level of IGFBP2 is significantly associated with poor survival, suggesting that blood IGFBP2 levels could be a prognostic biomarker for lung cancer." (PMID 24069370, 2013). "Because the lung cancer-resistant Car-R mouse has greater pulmonary expression of Igfbp5 and of Igfbp2 than the cancer-susceptible SWR/J strain, we hypothesized that overexpression of these genes may suppress lung tumorigenesis." (PMID 22973541, 2012). "As a secreted protein that potentially participates in cell signaling, our aim was to identify and screen for gene expression in lung cancer cells that depend on IGFBP2." (PMID 38918360, 2024). "Firstly, the expression of IGFBP2 in the bronchoalveolar lavage fluid and lung cancer tissues of 20 NSCLC patients with gefitinib tolerance was found to be significantly higher than that of non-tolerant patients." (PMID 38918360, 2024). "The mean expression of IGFBP2 was considerably higher in lung cancer patients than in controls, and it increased as the cancer progressed to an advanced stage." (PMID 38001653, 2023).
lung carcinoma (continued). "In a comprehensive study, 81 lung cancer patients and 36 healthy and benign pulmonary lesion participants were assessed for the expression of insulin-like growth factor (IGF) binding protein-2 (IGFBP2)." (PMID 38001653, 2023). "The expression was further validated in an additional cohort of 84 lung cancer patients, together with an evaluation of the prognostic and chemoresistant significance of IGFBP2." (PMID 38001653, 2023). "AHSG and IGFBP2 levels were increased in lung patients with malignant pleural effusion but those with nonmalignant pleural effusion, and the authors simultaneously demonstrated the extracellular function of IGFBP2 in migration in lung cancer cells." (PMID 35494074, 2022). "As shown in recent studies, elevated IGFBP2 expression and activated FAK have been causally associated with dasatinib resistance in lung cancer cells, and administration of a combination of dasatinib with an FAK inhibitor can overcome this resistance." (PMID 30609749, 2019). "As a result, the mean expression of IGFBP2 in lung cancer patients was significantly higher than that in controls and increased with lung cancer progressed to advanced stage." (PMID 29500455, 2018). "A multivariate analysis showed that lung cancer patients with higher IGFBP2 had a poor survival outcome (HR = 8.22; 95%CI 1.78–37.92, P = 0.007) after adjustment for histopathology, surgery, pathology, age, smoking history and stage." (PMID 29500455, 2018). "Presently we found that the mean IGFBP2 in the circulation was significantly higher in lung cancer patients than that in healthy and benign participants; and increased with disease progressed to advanced stage." (PMID 29500455, 2018). "IGFBP4 is generally considered to have a negative regulatory role on IGF-1, for example, both IGFBP4 and IGFBP2 were found to be down-regulated through promoter hypermethylation in lung carcinomas." (PMID 28443133, 2017). "Our results provide the first evidence that the serum levels of anti-IGFBP-2 antibodies in patients with lung cancer are higher than that of patients with benign lung diseases and normal controls." (PMID 23165420, 2013). "A multivariate analysis showed that lung cancer patients with blood IGFBP2 > 160.9 ng/ml had a poor survival outcome (hazard ratio = 8.76, 95% CI 1.12-68.34, p=0.038 after adjustment for tumor size, pathology, and stage)." (PMID 24069370, 2013). "The results showed that the mean plasma concentration of IGFBP2 in lung cancer patients (388.12±261.00 ng/ml) was significantly higher than that in healthy controls (219.30±172.84 ng/ml, P=2.4 x 10-7)." (PMID 24069370, 2013). "Serum IGFBP-2 levels in patients with lung cancer were higher than that of benign lung disease (1,036.015, 766.304, 209.185–2,885.543 ng/ml), but the difference was not significant (P=0.148)." (PMID 23165420, 2013). "To determine if that is true, we analyzed the IGFBP2 levels in plasma of lung cancer patients and healthy case-matched controls." (PMID 24069370, 2013). "When stratifying the analysis by American Joint Committee on Cancer stage for lung cancer, interestingly, a modest difference in anti-IGFBP-2 antibody levels was observed between early cancers and advanced cancers in lung cancer." (PMID 23165420, 2013). "IGFBP2 was increased in all types of lung cancer, including adenocarcinoma, squamous cell cancer, and small-cell cancer, regardless of patients’ age, sex, or smoking status." (PMID 24069370, 2013). "We then determined the specificity and sensitivity of using plasma IGFBP2 levels for lung cancer diagnosis." (PMID 24069370, 2013). "Our recent proteomic study on primary NSCLC tumor tissues showed that a subset of lung cancer patients had a dramatic increase of IGFBP2 in their primary tumor tissue." (PMID 24069370, 2013). "We found that the combination of serum IGFBP-2 and anti-IGFBP-2 antibodies can augment the discriminative power for lung cancer with the sensitivity of 85.7% and the specificity of 57.5%." (PMID 23165420, 2013).